SMAD4 (SMAD family member 4)
Diseases named in the same sentence as SMAD4 in open-access papers (continued):
Sharing a sentence is not in itself a finding about the gene and the disease.
pancreatic cancer (continued). "The loss of SMAD4 expression significantly correlated with poor OS in patients with cancers, such as pancreatic cancer, colorectal cancer, and prostate cancer." (PMID 34307117, 2021). "On the other hand, one previous report has shown that the percentage of overall inactivation or loss of SMAD4 in pancreatic cancer is 60%–90% and our result (74.1%) is within the range." (PMID 32737864, 2021). "SMAD4 loss renders pancreatic cancer resistance to radiotherapy due to ROS induction and promotion of autophagy." (PMID 33669845, 2021). "The tumor suppressor gene SMAD4, mutated or deleted in 55% of pancreatic cancer, has been implicated in treatment resistance via upregulation of autophagy." (PMID 34002944, 2021). "Mutations in SMAD4 are related to advanced disease, poor overall survival, and recurrence after localize treatment in resectable pancreatic cancer." (PMID 35083150, 2021). "Given the autophagy‐mediated treatment‐resistance in SMAD4 mutated or deleted pancreatic cancer cells, this study retrospectively examined the effect of HCQ with neoadjuvant chemotherapy according to SMAD4 status." (PMID 34002944, 2021). "Mutations of Smad4 have been detected in pancreas cancer, colon cancer, cholangiocarcinoma cancer, and gastric cancers, suggesting an important tumor suppressor function of Smad439–43." (PMID 34381046, 2021). "As a result of SMAD4 loss, the advantage of growth for pancreatic cancer cells in the late PanIN stage (PanIN-3) is provided by nullifying the signals arbitrated by TGF-β." (PMID 33918146, 2021). "In pancreatic cancer, alterations of TGF-β signaling occur through the mutation of the genes involved in the pathway (including SMAD4); this activity is present in 47% of pancreatic cancer patients." (PMID 34880877, 2021). "While in most cancer cells, TGFβ-induced EMT is associated with pro-oncogenic response, in pancreatic cancer cells with an intact TGFβ/SMAD4 pathway, it was found associated with apoptosis in a KLF5 repression-dependent manner." (PMID 31822964, 2020). "The tumor suppressor SMAD4 (DPC4 [deleted in pancreatic cancer 4]) was chosen as a model, as its loss is one of the best characterized events in pancreatic cancer development." (PMID 32420409, 2020). "Previously, SMAD4 gene mutation was reported to be associated with the poor prognosis of patients with pancreatic cancer." (PMID 32950968, 2020). "Another study demonstrated that SMAD4 mutation was associated with pancreatic tumor stages; the degree of inactivation was 31% in high-grade stage neoplasms (Pan IN-3), while none was found in the low-grade lesions (Pan IN-1-2)." (PMID 32781778, 2020). "Considering the genetic diversity of PDAC in clinic, We also tested Nano-sapper in Panc02 transplantation model which has both Kras and Smad4 (occurred in ~50% of pancreatic cancers) mutations." (PMID 32001695, 2020). "Some studies have shown that the prognosis of pancreatic cancer with a SMAD4 mutation in the MH2 domain is poor." (PMID 31684910, 2019).
pancreatic cancer (continued). "The 4th most frequently mutated gene in PDAC is SMAD4 (previously designated Delete in Pancreatic Cancer 4; DPC4), encoding a transcriptional regulator that is a central component in the TGF-β superfamily signaling cascades." (PMID 31480737, 2019). "SMAD4 mutations are relatively specific in pancreatic cancer and are central mediators of the transforming growth factor beta (TGF-β) signaling pathway." (PMID 31417657, 2019). "Compared with 35% of pancreatic cancer and 12% of colon cancer cases, SMAD4 mutation in other types of cancers has occurred at lower rates." (PMID 31867281, 2019). "Smad4 is a major downstream protein of the TGF- β1 signaling pathway and Smad4 mutation is one of the four pancreatic cancer cell driver gene mutations." (PMID 31350453, 2019). "At the same time, mutations of Smad4 are more frequent in some cancers, such as colon cancer, gastric cancer, and pancreatic tumors." (PMID 31632911, 2019). "We showed that the loss of SMAD4 was associated with an activated Shh signaling pathway in resectable pancreatic cancer." (PMID 31417657, 2019). "SMAD4 acts as a tumor suppressor in carcinomas of the pancreas and GI tract, where deletions or inactivating mutations in the SMAD4 gene have been reported." (PMID 30824765, 2019). "miR-494 is also induced by TGF-β at the pri-miRNA level in a Smad4-dependent manner, while miR-494 shows reduced expression in pancreatic cancer cells with a loss of Smad4." (PMID 29958433, 2018). "In tumors with activated TGFβ signaling such as hepatocellular cancer, elevated SMAD4 has been shown to mediate tumor promoting signaling, while in other cancers such as pancreatic cancer, deletion of SMAD4 is associated with tumor progression and metastasis." (PMID 29861845, 2018). "Colorectal cancer and pancreatic cancer are all gastroenterological cancers and share some similar genetic backgrounds, such as mutations in Kras and SMAD4." (PMID 29476053, 2018). "Pancreatic cancer has detected loss of function or truncating mutations of TGFβRI, TGFβRII, Smad2, and Smad4 genes." (PMID 28794854, 2017). "The study in 90 pancreatic cancer patients showed that SMAD4 mutations were present in 17/90 patients (19%) and gene mutation status was significantly associated with overall survival (p = 0.006)." (PMID 28452926, 2017). "SMAD4 loss is frequently observed in pancreatic cancer (more than 50%), but it is an event occurring at late stages of cancer development since it is rarely observed in pre-invasive pancreatic neoplasia." (PMID 29156578, 2017). "SMAD4 is a tumor-suppressive gene that can cause cell cycle arrest and apoptosis of epithelial cells, and is inactivated by mutation in over half of pancreatic cancers." (PMID 28619094, 2017). "Loss of the tumour suppressor gene Smad4 (dpc4) is associated with the development of metastatic disease in pancreatic cancer." (PMID 28190636, 2017). "SMAD4 is frequently inactivated by genomic alterations, such as deletion or mutation, contributing to cancer progression in pancreatic cancer, colorectal cancer and prostate cancer." (PMID 28638102, 2017).
pancreatic cancer (continued). "Because DPC4 protein loss is correlated with SMAD4/DPC4 mutation, immunohistochemical staining for DPC4 protein is used as a diagnostic criteria of pancreatic cancer with lower cost than sequencing of SMAD4/DPC4." (PMID 28435405, 2017). "Mutations of SMAD4 occur in around 50% of pancreatic cancers, mostly leading to the loss of protein activated." (PMID 28452926, 2017). "In fact, some studies have shown that conditional loss of SMAD4 or TGFBR2 in Pdx1-Cre/LSL-KRas mice develop advanced aggressive pancreatic cancer." (PMID 29156578, 2017). "The multivariate analysis showed that the loss of SMAD4 predicted poor prognosis in patients with less advanced disease (likely Stage I to Stage II pancreatic cancer)." (PMID 28067794, 2017). "Studies on genetically engineered mouse models of pancreatic cancer with Smad4 mutation as well as Kras allowed a successful analysis on PDAC development and prognosis." (PMID 28067794, 2017). "Various components of the TGF-β signaling pathway have been shown to be mutated or altered in expression in certain types of carcinomas, such as DPC4, encoding the intracellular signal transducer Smad4, in pancreatic cancer." (PMID 28726720, 2017). "The prevalence of Smad4 mutations is about 50% in pancreatic carcinomas, but, in other tumor types, these mutations are less frequent." (PMID 28423626, 2017). "Mutations or deletions of SMAD4 have been associated with a decrease in the sensitivity of pancreatic cancer cells to H-1PV, which was traced back to the involvement of SMAD4 in parvovirus P4 promoter activation and ensuing NS1 expression." (PMID 25630937, 2015). "Smad4 deficiency can lead to rapid progression of pancreatic tumors in the context of activated KrasG12D; however, Smad4 deficiency alone is incapable of initiating pancreatic tumorigenesis and dispensable for normal pancreas development." (PMID 25803032, 2015). "SMAD4 mutations are present in twenty percent of pancreatic cancers and have been associated a poorer prognosis and increased metastases." (PMID 25714017, 2015). "LOH at 18q where SMAD4 gene is located occurs in 90% of pancreatic cancers while gene deletions and loss of protein expression occur in 50%." (PMID 24465802, 2014). "Defects in TGF-β signaling have been reported for the majority of pancreatic cancers, with deletions or mutations in Smad4 being most prevalent." (PMID 24944686, 2014). "A prior study from our institution suggested that SMAD4 loss correlates with an adverse outcome in patients with locally advanced pancreatic cancer receiving gemcitabine, oxaliplatin and cetuximab." (PMID 24465802, 2014). "The homozygous loss of Smad4 has been the basis for use of BxPC3 cells as a model for pancreatic cancer with defective TGF-β signaling." (PMID 24944686, 2014). "Further investigations will help to determine how this SNP is functionally associated with the SMAD4 signaling transduction and survival in pancreatic cancer patients." (PMID 24465802, 2014). "SMAD4 is a gastrointestinal malignancy-specific tumor suppressor gene found mutated in one third of colorectal cancer specimens and half of pancreatic tumors." (PMID 24625091, 2014). "SMAD4, also known as deleted in pancreatic carcinoma, locus 4 (DPC4), was first identified on the basis of frequent homozygous deletions and mutations affecting 18q21.1 in the pancreatic tumor, and was found to be involved in the TGF-β1 signaling pathway." (PMID 24625091, 2014).
pancreatic cancer (continued). "For instance, missense mutations in the Smad4 gene found in pancreatic cancer cells are associated with reduced nuclear translocation." (PMID 24386222, 2013). "SMAD4 was frequently inactivated in cancers and linked to activation of K-ras oncogene in pancreatic cancer." (PMID 23826135, 2013). "A role for Smad signaling in suppressing oncogenic K-Ras induced tumorigenicity is supported by a study demonstrating that inactivation of Smad4 accelerated K-Ras (inducing G12D mutation) induced pancreatic cancer development and progression." (PMID 24340014, 2013). "Loss of Smad4 expression correlates with both development of widespread metastasis and poor prognosis in pancreatic cancer patients." (PMID 24325450, 2013). "Studies have found homozygous deletions of Smad4 in 30% of pancreatic tumors, and inactivating intragenic mutation in conjunction with loss of the other allele in another 20% of cases." (PMID 24047375, 2013). "Previous studies demonstrated that SMAD4 was considered as a tumor suppressor and was frequently mutated or homozygously deleted in pancreatic cancer and colorectal cancer." (PMID 23826135, 2013). "This cell line is the only Smad4-deficient among the four pancreatic cancer cell lines we investigated." (PMID 23588713, 2013). "Smad4 was originally identified as a tumor suppressor and deletions or mutations in SMAD4 is common in solid cancers, including 50% of all pancreatic cancers." (PMID 23049692, 2012). "Smad4 mutations are common in pancreatic cancer and are associated with poor prognosis compared with patients that harbor a wild-type Smad4 in their tumors." (PMID 23049538, 2012). "Pancreatic cancer-associated Smad4 mutant proteins are more prone to ubiquitination and subsequent proteasome degradation than the wild-type Smad4." (PMID 23049538, 2012). "In particular, it has been reported that mutation or deletion of Smad4 is found in about 50% of pancreatic tumors and is correlated with poor prognosis." (PMID 22458379, 2012). "A number of studies have shown that loss of Smad4 is generally observed in pancreatic carcinogenesis, and inactivation of Smad4 is associated with poor prognosis in pancreatic cancer." (PMID 22860091, 2012). "We chose two cell lines, BxPC-3 cells which (like AsPC-1 cells and most pancreatic tumors) have mutated SMAD4 (here by homozygous deletion), and Hs700T cells which are wildtype for SMAD4 and have an intact TGFβ growth-inhibitory pathway." (PMID 21887346, 2011). "Of note, however, AsPC-1 cells (like most pancreatic cancers) harbor a mutated SMAD4, here SMAD4 (R100T), characterized to be inactivating." (PMID 21887346, 2011). "Genetically, homozygous deletion of Smad4 has been identified in pancreatic cancer and colorectal adenocarcinomas; germline mutation of Smad4 causes Juvenile Polyposis Syndrome (JPS)." (PMID 22204491, 2011). "The TGFβ growth suppressive pathway is commonly disrupted in pancreatic cancer, most often through mutation/deletion of SMAD4, but also through inactivation/loss of TGFβRI and TGFβRII." (PMID 21887346, 2011). "Recent studies have shown that SMAD4 inactivation is associated with the advanced disease state of various human tumors, including pancreatic carcinoma, esophageal carcinoma, colorectal carcinoma, renal cell carcinoma, as well as breast carcinoma." (PMID 21791112, 2011). "Smad4 was initially identified as a frequent deletion target in pancreatic carcinomas, and Smad4 deletions or mutations were also found in colon, breast, and lung cancers, albeit with less frequency." (PMID 22204598, 2011).
pancreatic cancer (continued). "Mutations in the TGFβ pathway observed in pancreatic cancer principally concern SMAD4: Its inactivation is observed in about 55% of cases and is associated with poor prognosis." (PMID 24281218, 2010). "SMAD4/DPC4 was found to be homozygously deleted in about 30% of pancreatic carcinomas and inactivated by intragenic mutation in another 20% of the tumors." (PMID 20565773, 2010). "Approximately 50% of pancreatic carcinomas, 20% of colon carcinomas, and 10% of lung cancers exhibit mutations in SMAD4, and mutations in SMAD2 have been found in ~7% of colorectal and lung cancers." (PMID 20565773, 2010). "Somatic ACVR1B gene mutations have been found in pancreatic carcinoma and Smad2 and Smad4 are mutated in colorectal and pancreatic carcinomas." (PMID 19538713, 2009). "Smad4 deficient pancreatic carcinoma cell lines express increased levels of phosphorylated Smad2 (P-Smad2)." (PMID 19849841, 2009). "About half of pancreatic carcinomas contain either homozygous deletions of the SMAD4 locus or inactivating mutations in one allele associated with LOH, and a resultant loss of SMAD4 expression in pancreatic carcinoma has been documented." (PMID 19352382, 2009). "Here, we present detailed studies of the three promoters of the genes encoding LM-332 in human colorectal adenoma cells and in Smad4-deficient and Smad4-reexpressing colorectal and pancreatic carcinoma cells." (PMID 18664273, 2008). "To unravel the mechanisms that underlie Smad4-mediated tumor suppression we have established derivatives of Smad4-deficient human colorectal and pancreatic carcinoma cells, in which Smad4 is stably restored through gene transfer." (PMID 18664273, 2008). "Far more interesting however, was the finding that SMAD4 expression within excised pancreatic carcinoma was associated with a worse outcome." (PMID 17587453, 2007). "In the five pancreatic cancer cell lines with SMAD4 mutations, including Capan-1, CFPAC, Colo-357, FG, and BxPC-3, type I collagen promotes maximal adhesion, migration, and proliferation." (PMID 16622460, 2006). "To date, a significant number of Smad4 point mutations have been found only in pancreatic carcinomas (50–60%), biliary tract carcinomas (15%) or colorectal carcinomas (5–20%)." (PMID 12569386, 2003). "Specifically, the SMAD4 deficiency in pancreatic cancer cells could facilitate the intracellular accumulation of ROS, which acted as a danger signal to activate the autophagic influx." (PMID 41041050, 2025). "Notably, it lacks the KRAS mutation and features a homozygous deletion of the SMAD4 gene, making it a valuable resource for studying the genetic landscape of pancreatic cancer." (PMID 40190550, 2025). "The enhanced dependence on the BMP/SMAD1/5/9 pathway in SMAD4-deficient contexts could potentially explain why CHRDL1 exhibits more pronounced metastasis-suppressing effects in pancreatic cancer." (PMID 40837015, 2025). "Finally, a significant minority of PDACs contain mutations in the SMAD4 gene, also sometimes referred to as Deleted in Pancreatic Cancer-4 (DPC4), with such mutations being less common in other types of cancer." (PMID 40723241, 2025). "Additionally, a study exploring SMAD4 gene mutation’s impact on pancreatic cancer response to radiotherapy reveals that SMAD4 depletion induces resistance to ionizing radiation." (PMID 38666907, 2024). "Studies suggest that analyzing Smad4 protein expression in pancreatic cancer cell lines can reveal insights into the molecular mechanisms driving pancreatic cancer, offering avenues for novel therapeutic strategies targeting Smad4-deficient tumors, to improve patient outcomes." (PMID 39596873, 2024). "Interestingly, TF activity analysis showed that Ep_VGLL1 can be distinguished by the high activities of KLF5 and SOX4, the TF pair marking the tumorigenic SMAD4-deficient pancreatic cancer cells under the TGF-β milieu." (PMID 38297291, 2024).